FABP7 (fatty acid binding protein 7)
Diseases named in the same sentence as FABP7 in open-access papers (continued):
Sharing a sentence is not in itself a finding about the gene and the disease.
breast cancer (continued). "In this study, correlation analysis for the expression of prognostic LRGs (FABP7 and NDUFAB1) and immune cell infiltration in breast cancer was also performed using the ssGSEA R package." (PMID 35562758, 2022). "Kaplan–Meier survival analysis results identified the prognostic value of FABP7 and NDUFAB1 in breast cancer patients." (PMID 35562758, 2022). "FABP7 controls the expressions of metabolic and invasion-related proteins, supporting glycolysis and lipid droplet accumulation in HER2 positive breast cancer brain metastases." (PMID 34685621, 2021). "When we applied heteroDE to breast cancer samples, we identified 7 cfRNA biomarkers (SCGB2A2, CASP14, FABP7, CRABP2, VGLL1, SERPINB5, TFF1), 3 of which (FABP7, SCGB2A2, CASP14) overlap with previously identified DCB genes." (PMID 33883548, 2021). "While studies insinuate that HIF-1α induces cells to increase their lipid uptake through FABP7 for energy production, more work is required to elucidate the role of HIF-1α in lipid metabolic alteration of breast cancer." (PMID 33266219, 2020). "We found a strong mutual exclusivity between FABP7 and UCP1 expression in the METABRIC and TCGA breast cancer cohorts." (PMID 32647572, 2020). "FABP7 is a potential favorable biomarker and predicts better response to NAC in breast cancer patients." (PMID 33292226, 2020). "In the present study, analysis of three genomic profiles from the GEO indicated that FABP7 and ESR1 were essential indicators of response to anthracycline and taxanes in breast cancer." (PMID 33292226, 2020). "Two differentially expressed genes, including FABP7 and ESR1, were identified to be potential indicators of response to anthracycline and taxanes for breast cancer." (PMID 33292226, 2020). "Gene set analysis revealed that in human breast cancer cell lines the expression of these seven genes (MUC1, PLAU, FABP7, SPARC, HAS2, HAS3, SOX4) are higher in basal-B subtype compared to other subtypes." (PMID 29435170, 2018). "Down-regulation of FABP7 expression by siRNAs significantly reduces the migration of melanoma cell lines, an RCC cell line, breast cancer cells, and malignant glioma cells." (PMID 28292269, 2017). "In contrast, knockdown of FABP7 expression inhibits the proliferation of melanoma cells, an RCC cell line, a breast cancer cell line, and glioblastoma cells." (PMID 28292269, 2017). "In view of this fact, we examined the expression of FABP7 and HMGCS2 together with several other apocrine protein markers in the MDA-MB-453 breast cancer cell line." (PMID 25389781, 2014). "Ectopic expression of FABP7 induces cell differentiation and suppresses tumor growth and was shown to mediate the cytotoxicity of DHA to breast cancer cells." (PMID 16623952, 2006). "The prognostic gene signature constructed with FABP7 and NDUFAB1 was significantly related to immune cell infiltration and could predict the overall survival rate with above average correctness of breast cancer patients." (PMID 35562758, 2022). "By analysing the results, univariate analyses identified the expression of FABP7 and NDUFAB1, and the stage of pT, pN, and pM were the factors that could affect the prognosis of breast cancer patients." (PMID 35562758, 2022). "Furthermore, using a breast cancer cell line, HCC1806, we tested the effect of FABP7 knockdown on cellular physiology including thermogenesis." (PMID 32647572, 2020). "The intersection identified a total of 2 differentially expressed genes, including FABP7 and ESR1, might be essential indicators of chemotherapeutic efficacy in breast cancer." (PMID 33292226, 2020). "FABP7-positive, compared to FABP7-negative, breast cancer patients experienced significantly longer disease-free survival and breast cancer specific survival." (PMID 21771320, 2011). "Furthermore, as lipid metabolism regulators, FABP7 and NDUFAB1 might have the potential to elucidate the mechanism of breast cancer cell invasion and metastasis." (PMID 35562758, 2022).
breast cancer (continued). "Finally, fatty acid binding protein 7 (FABP7) and αB-crystallin have preferentially higher expression in the basal-like subtype at both the protein and DNA level making them prime candidates for further investigation as biomarkers of basal-like breast cancer." (PMID 24281106, 2010). "However, the 5 breast cancer patients with the highest apparent tumor fraction did not have detectable levels of FABP7 in plasma, suggesting that other factors beyond tumor fraction may affect DCB abundance in cfRNA." (PMID 33883548, 2021). "There is also a striking correlation of expression of each gene with specific types of breast cancer, ER positive to UCP1, and ER negative to FABP7." (PMID 32647572, 2020). "In contrast to these in vitro experimental results, we found no substantial correlation of FABP7 and UCP1 expression on patient survival in the METABRIC and TCGA breast cancer cohorts." (PMID 32647572, 2020).
glioma (42 papers, 2005 to 2026). A benign or malignant brain and spinal cord tumor that arises from glial cells (astrocytes, oligodendrocytes, ependymal cells). "Conversely, FABP7 overexpression was associated with increased LD accumulation in human glioma cells, underscoring the importance of FABP7 for LD formation." (PMID 38786059, 2024). "Other fatty acid-binding proteins such as FABP3, FABP5, FABP6 and FABP7 have been also implicated in glioma migration or invasion." (PMID 37120445, 2023). "The results of this study showed that FABP7 was overexpressed in glioma and that higher FABP7 expression was associated with poor patient prognosis and poor response to apatinib." (PMID 35783014, 2022). "Levels of FABP7 expression and their association with the clinicopathologic characteristics of glioma patients were analyzed in the CGGA database." (PMID 35783014, 2022). "Further analysis of the association of FABP7 expression with clinicopathologic characteristics of patients in the CCGA dataset showed that the level of FABP7 expression in patients with glioma correlated significantly patient age and tumor grade (p < 0.001)." (PMID 35783014, 2022). "FABP7 was highly expressed in glioma samples, with higher FABP7 expression associated with poorer patient prognosis and more advanced clinicopathological features." (PMID 35783014, 2022). "Kaplan–Meier survival analysis of clinical data from the CGGA dataset showed that high FABP7 expression was significantly associated with reduced survival in glioma patients (p < 0.001)." (PMID 35783014, 2022). "We also observed expression of transcripts encoding the neural progenitor marker BLBP/FABP7 in neural stem cells and in glioma-derived cell spheres." (PMID 21297991, 2011). "Notably, the nuclear localization of FABP7 has been linked to glioma progression, particularly in oncogene-mutated aggressive subtypes, such as EGFR-amplified and IDH1 wild-type GBM." (PMID 39596296, 2024). "High FABP7 expression is associated with poor prognosis in glioma patients." (PMID 35783014, 2022). "Additionally, other protein from the fatty acid-binding protein family, FABP7, has also been implicated as a glioma prognostic marker, and was correlated with the recurrence of several types of gliomas." (PMID 35784465, 2022). "Indeed, mutated FABP7 is restricted only in the cytoplasm, altering the rate of glioma proliferation." (PMID 34716958, 2022). "In glioma cells, fatty acid binding protein 7 (FABP7) internalizes long-chain fatty acids to promote lipid droplet formation, while in astrocytes with FABP7 knockout, the ability of ROS to induce lipid droplet formation is diminished." (PMID 40618174, 2025). "FABP7-specific antisense oligodeoxynucleotides inhibited EGF-induced migration in SF763 glioma cells." (PMID 40097417, 2025). "Single-cell expression atlas analysis revealed that FABP7 is predominantly expressed in glial and malignant cell populations within gliomas and shows nuclear localization in NSCs." (PMID 39596296, 2024). "An analysis of a single-cell expression atlas revealed that FABP7 is predominantly expressed in the glial lineage and malignant cell populations in gliomas, with nuclear localization in their parental NSCs." (PMID 39596296, 2024). "Our study offers a detailed understanding of how FABP7 contributes to tumor progression by reshaping the oncogenic gene expression landscape within glioma cells, specifically through its influence on key cancer-associated pathways." (PMID 39596296, 2024). "This is reminiscent of a recent study proposing FABP7 as a potential biomarker for predicting the prognosis and efficacy of anti-angiogenic drugs for the treatment of glioma." (PMID 39596296, 2024). "Herein, we identified high expression of FABP7 in IDH1wt anaplastic glioma and GB compared to IDH1mut glioma and found that FABP7 is highly localized in nucleus in IDH1wt anaplastic glioma and GB." (PMID 34716958, 2022).
glioma (continued). "Immunohistochemistry showed that FABP7 expression was higher in glioma patients with poor survival after apatinib treatment." (PMID 35783014, 2022). "The present study found that high expression of FABP7 correlated with poor prognosis in patients with glioma." (PMID 35783014, 2022). "In this study, we have explored the expression and localization of FABP7 in current separated grade of glioma with focus on IDH1 mutation and how FABP7 regulates cellular activity of GB focusing on the epigenetic regulation of caveolin‐1." (PMID 34716958, 2022). "In this study, we newly demonstrated that FABP7 is highly expressed and localized in nuclei in IDH1wt glioma." (PMID 34716958, 2022). "We firstly evaluated the expression level of FABP7 in IDH1wt and IDH1mut glioma using Pan‐Cancer Atlas of TCGA in cBioPortal and TCGA database." (PMID 34716958, 2022). "Analysis of the levels of FABP7 mRNA in the CGGA, TCGA, and GEO datasets showed that FABP7 mRNA was overexpressed in patients with glioma." (PMID 35783014, 2022). "Bioinformatics analysis, including survival, receiver operating characteristic curve, and univariate and multivariate Cox analyses, showed that FABP7 was independently prognostic of outcomes in glioma patients." (PMID 35783014, 2022). "Immunohistochemical results showed that FABP7 expression was significantly higher in glioma patients with poor prognosis." (PMID 35783014, 2022). "The present study investigated the relationship between FABP7 expression and prognosis in glioma patients by bioinformatics analysis, as well as immunohistochemically evaluating the effect of FABP7 expression on the efficacy of antiangiogenic drugs." (PMID 35783014, 2022). "FABP7 expression in the tissues of glioma patients treated with apatinib was evaluated immunohistochemically." (PMID 35783014, 2022). "In this study, we demonstrate that FABP7 is highly expressed and localized in nuclei in IDH1wt glioma." (PMID 34716958, 2022). "The present study evaluated the potential role of FABP7 in glioma by analyzing its expression in a large number of human gliomas." (PMID 35783014, 2022). "EGFR gene amplification has been observed in pediatric low-grade gliomas that disseminate possibly through a mechanism of induced FABP7 nuclear translocation." (PMID 26199775, 2015). "Higher expression of FABP7 was shown to negatively correlate with survival of GBM patients and the over expression of FABP7 increased the migration of glioma cells in vitro." (PMID 24475040, 2014). "In fact, all four members of the NFI family of transcription factors play key roles in the regulation of FABP7 in glioma cell lines." (PMID 21771320, 2011). "Study of human glioma cell lines indicate that FABP7 mRNA and protein expression were positively correlated with glial fibrilary acidic protein which is a marker of differentiation of astrocytes." (PMID 19014610, 2008). "Variation in sub-cellular localization of FABP7 has been reported in developing radial glia cells, glioma cell lines and glioblastoma multiforme (GBM) specimens." (PMID 18826602, 2008). "Although FABP7 is a cytoplasmic protein, its varying subcellular localization between nucleus and cytoplasm has been reported in developing brain, glioma cell lines, and GBM specimens." (PMID 16623952, 2006). "The goals of this study were to determine a plausible biological role for FABP7 in glioma pathogenesis." (PMID 16623952, 2006). "In this study, we examined the expression patterns and subcellular localization of FABP7 in specimens from normal individuals, from individuals with gliosis only, and from patients with gliomas differing in grade and histology." (PMID 16623952, 2006). "Such differential patterns in both expression and subcellular localization of FABP7 are also seen in cells with astrocytic features in various types of glioma." (PMID 16623952, 2006).
glioma (continued). "EGFR activation increased nuclear FABP7 immunoreactivity in a glioma cell line in vitro, and inhibition of FABP7 expression suppressed EGF-induced glioma-cell migration." (PMID 16623952, 2006). "FABP7 immunoreactivity in grade I pilocytic astrocytoma was predominantly cytoplasmic, whereas nuclear FABP7 was detected in other types of infiltrative glioma." (PMID 16623952, 2006). "It has recently been shown that FABP7 translocates to the nucleus and interacts with nuclear factors (e.g., ACLY, RXRα) to modulate gene expression associated with cellular physiology and metabolism in both astrocytes and glioma cells." (PMID 39596296, 2024). "In parallel, the immunohistochemical staining data revealed that the expression levels of FABP7 protein in tumor tissues were significantly higher than in normal tissues, particularly in gliomas, with gradual declines in staining intensity in other tumor types." (PMID 39596296, 2024). "This suggests that the differing intracellular properties of NSCs and their differentiated glioma cells could influence FABP7 localization and function." (PMID 39596296, 2024). "Univariate and multivariate Cox regression analyses of the CGGA dataset were performed to determine whether FABP7 is an independent prognostic indicator of survival in glioma patients." (PMID 35783014, 2022). "Therefore, the present study analyzed the levels of expression of FABP7 in glioma and the relationship between FABP7 expression and clinicopathological features of glioma patients in the CGGA and TCGA databases." (PMID 35783014, 2022). "Univariate analysis indicated that high FABP7 expression, PRS type, tumor grade, age, chemotherapy status, IDH mutation status, and 1p19q codeletion status were associated with reduced OS in patients with glioma." (PMID 35783014, 2022). "FABP7, which is important for glioma angiogenesis, may serve as an independent prognostic predictor in glioma patients." (PMID 35783014, 2022). "FABP7 may be prognostic of survival outcomes in patients with glioma and may influence tumor progression by promoting tumor angiogenesis." (PMID 35783014, 2022). "In addition, HPA results and western blotting of paired tumor and normal tissue samples from 10 patients with glioma showed that the level of FABP7 protein was higher in glioma than in normal tissues." (PMID 35783014, 2022). "Moreover, evaluation of the TIMER website showed that FABP7 was highly expressed in many tumors, especially in glioma." (PMID 35783014, 2022). "Similarly, the present study showed that FABP7 was an independent prognostic marker for survival in patients with glioma." (PMID 35783014, 2022). "In addition, evaluation of data from the HPA website showed that FABP7 protein levels were markly higher in glioma than in normal tissues." (PMID 35783014, 2022). "Glioma and accompanying normal tissue samples selected from sixteen glioma patients who were treated with apatinib were assessed immunohistochemically using antibodies to FABP7." (PMID 35783014, 2022). "FABP7 expression is closely related to the occurrence and development of glioma." (PMID 35783014, 2022). "However, most studies of fatty acid binding protein in glioma were limited to FABP7, which was found to be overexpressed and thought to be involved in tumor proliferation, invasion, and migration." (PMID 34685761, 2021). "Moreover, FABP7 is co-expressed with Sox2 in gliomas and FABP7+/Sox2+ cells are found more abundantly in GBMs compared to lower grade astrocytomas, indicating FABP7 as a potential GSC biomarker." (PMID 31752169, 2019). "Further, overexpression of FABP7 enhances the migration of glioma cells." (PMID 28292269, 2017). "FABP7 plays a role in neurogenesis and is a marker of glioma stem cells." (PMID 28382934, 2017). "Moreover, FABP7 enhances the migration of glioma cells, and an antibody against FABP7 inhibits cell migration." (PMID 28292269, 2017).